MIR450A1 (microRNA 450a-1)
Synonyms: hsa-mir-450; hsa-mir-450-1; hsa-mir-450a-1; MIRN450; MIRN450-1; MIRN450A-1; MIRN450A1; mir-450a-1
Gene: MicroRNA gene on chromosome X (134,540,341 to 134,540,431, reverse strand). Ensembl gene ENSG00000199132.
Gene Ontology:
Biological process: miRNA-mediated post-transcriptional gene silencing
Cellular component: RISC complex
Homologues: Orthologues: chimpanzee ptr-mir-450a-1 (100% identical), macaque mml-mir-450a-1 (97% identical), guinea pig MIR450A1 (92% identical), pig ssc-mir-450a (90% identical), dog MIR450A (89% identical), mouse Mir450-1 (86% identical). Paralogues in human: MIR450A2 (87% identical), MIR450B (69% identical).